ADCYAP1 (adenylate cyclase activating polypeptide 1)
Description:
PACAP is a neuropeptide involved in diverse array of physiological processes through activating the PACAP subfamily of class B1 G protein-coupled receptors: VIP receptor 1 (VIPR1), VIP receptor 2 (VIPR2), and PACAP type I receptor (ADCYAP1R1). Exerts neuroprotective and general cytoprotective effects due to anti-apoptotic, anti-inflammatory, and antioxidant actions. Promotes neuron projection development through the RAPGEF2/Rap1/B-Raf/ERK pathway. In chromaffin cells, induces long-lasting increase of intracellular calcium concentrations and neuroendocrine secretion (By similarity). Involved in the control of glucose homeostasis, induces insulin secretion by pancreatic beta cells (By similarity). PACAP exists in two bioactive forms from proteolysis of the same precursor protein, PACAP27 and PACAP38, which differ by eleven amino acid residues in the C-terminus.
Synonyms: PACAP
Tractability: Small molecule: a structure with a bound ligand is known. Antibody: its Gene Ontology location is reachable by antibodies, with high confidence; UniProt places it where antibodies can reach, with medium confidence; UniProt predicts a signal peptide or a membrane-spanning region.
Gene: Protein-coding gene on chromosome 18 (904,871 to 912,172, forward strand). Ensembl gene ENSG00000141433.
Subcellular location: Secreted
Pathways (Reactome):
Signal Transduction: G alpha (s) signalling events; Glucagon-type ligand receptors; NGF-independant TRKA activation
Gene Ontology:
Molecular function: neuropeptide hormone activity; peptide hormone receptor binding; pituitary adenylate cyclase activating polypeptide activity; protein binding; signaling receptor binding; type 1 vasoactive intestinal polypeptide receptor binding; type 2 vasoactive intestinal polypeptide receptor binding; hormone activity
Biological process: adenylate cyclase-activating G protein-coupled receptor signaling pathway; neuron projection development; neuropeptide signaling pathway; positive regulation of chemokine (C-C motif) ligand 5 production; positive regulation of ERK1 and ERK2 cascade; positive regulation of GTPase activity; positive regulation of protein kinase activity; positive regulation of transcription by RNA polymerase II; regulation of G protein-coupled receptor signaling pathway; regulation of protein localization; activation of adenylate cyclase activity; cell-cell signaling; female pregnancy; insulin secretion; positive regulation of cAMP/PKA signal transduction; positive regulation of cold-induced thermogenesis; positive regulation of cytosolic calcium ion concentration; positive regulation of growth hormone secretion
Cellular component: extracellular region; neuron projection; perikaryon
Genetic constraint (gnomAD): Loss-of-function variants: 6 observed, 13.71 expected, observed/expected ratio (o/e) 0.44, 90% interval 0.24 to 0.86. The upper end of that interval is the gene's LOEUF score, 0.86, which puts it in group 3 of 6, group 1 being the genes least tolerant of losing a copy. Missense variants: 305 observed, 240.86 expected, observed/expected ratio (o/e) 1.27, 90% interval 1.15 to 1.39. Synonymous variants: 134 observed, 108.21 expected, observed/expected ratio (o/e) 1.24, 90% interval 1.08 to 1.43.
Homologues: Orthologues: chimpanzee ADCYAP1 (90% identical), guinea pig ADCYAP1 (86% identical), pig ADCYAP1 (84% identical), rabbit ADCYAP1 (83% identical), macaque ADCYAP1 (82% identical), mouse Adcyap1 (82% identical), dog ADCYAP1 (79% identical), rat Adcyap1 (69% identical), tropical clawed frog adcyap1 (55% identical), zebrafish adcyap1b (54% identical), zebrafish adcyap1a (47% identical). Paralogues in human: VIP (28% identical), GHRH (19% identical).
Diseases named in the same sentence as ADCYAP1 in open-access papers:
ADCYAP1 is named in the same sentence as 124 diseases in open-access papers, as found by Europe PMC text mining. Sharing a sentence is not in itself a finding about the gene and the disease. The quoted sentences say what the papers report.
migraine (93 papers, 2016 to 2026). "ADCYAP1 is a member of the circadian entrainment pathway and considered a potential target for therapies to ameliorate drug abuse, migraine, stress-related psychopathologies and inflammatory diseases." (PMID 33834688, 2021).
Anxiety (17 papers, 2016 to 2026). Intense feelings of nervousness, tension, or panic often arise in response to interpersonal stresses. "To illustrate this with an example, we present a loop involving Adcyap1, an important stress- and estrogen-sensitive gene implicated in anxiety-related behavior." (PMID 36307876, 2022). "Pituitary adenylate cyclase activating polypeptide (PACAP, Adcyap1) is a neuromodulator implicated in anxiety, metabolism and reproductive behavior." (PMID 29905528, 2018). "Furthermore, changes in CTCF looping around genes such as Adcyap1 and Thbs2 are associated with sex- and oestrous cycle-dependent gene expression differences and further provide a possible link between 3D genome changes and anxiety-related behavioural phenotypes." (PMID 35705546, 2022). "Other genes previously linked to mood, anxiety, or trauma-related disorders included protein zeta-1 (FEZ1), ADCYAP1, BRSK2, catenin alpha 3 (CTNNA3), and par-3 family cell polarity regulator (PARD3)." (PMID 34799556, 2021). "The gene ADCYAP1 is highly conserved among birds and mammals, and encodes the protein PACAP that together with its selective receptor PAC1 is integral to anxiety behavior and stress responses in the limbic system of the brain." (PMID 26881054, 2016). "We also hypothesized that altered Adcyap1 and Adcyap1r1/PAC1R content of the EWcp may be associated with increased anxiety and a depression-like state." (PMID 37511603, 2023). "Importantly, these peptidergic neurons were shown to co-express PACAP (Adcyap1) mRNA, and we saw their recruitment in various models for depression and anxiety applied in mice lacking one or both functional Adcyap1 gene alleles." (PMID 37511603, 2023).
depression (15 papers, 2015 to 2025). "Methylation analyses of 9 promoter/regulatory regions of genes known to be implicated in depression/PTSD (ADCYAP1, BDNF, CRHR1, DRD2, IGF2, LSD1/KDM1A, NR3C1, OXTR, SLC6A4) were performed on DNA from blood samples by the MassARRAY EpiTYPER platform, with MassCleave settings." (PMID 36001138, 2023). "For example, an SNP3 (rs1893154) in the ADCYAP1 gene is associated with major depressive disorder (MDD) in humans, albeit in a non-sex-specific manner." (PMID 39975969, 2025).
ischemia (13 papers, 2012 to 2023). A hypoperfusion of the BLOOD through an organ or tissue caused by a PATHOLOGIC CONSTRICTION or obstruction of its BLOOD VESSELS, or an absence of BLOOD CIRCULATION. "We previously demonstrated the exacerbation of cell death in Adcyap1+/− mice to compare with a WT mouse after ischemia and SCI." (PMID 25889720, 2015).
post-traumatic stress disorder (7 papers, 2013 to 2024). An anxiety disorder precipitated by an experience of intense fear or horror while exposed to a traumatic (especially life-threatening) event. "This group included Adcyap1 (adenylate cyclase activating polypeptide 1, also known as PACAP), which is associated with post-traumatic stress disorder (PTSD)." (PMID 34127022, 2021).
schizophrenia (7 papers, 2012 to 2024). A major psychotic disorder characterized by abnormalities in the perception or expression of reality. "However, in a recent subsequent functional genomics study in schizophrenic patients, PACAP (ADCYAP1) was identified as a top risk gene to be involved in schizophrenia suggesting a potential important role for PACAP in the pathogenesis of schizophrenia." (PMID 28125634, 2017). "Three human genes, ADCYAP1, PSORS1C2, and BTNL2, are associated with neuronal phenotypes, such as schizophrenia." (PMID 34542594, 2021). "Other disease-associated loci with human-specific gain selectively in PFC neurons include ADCYAP1, a schizophrenia and movement disorder gene that is part of a cAMP-activating pathway also implicated in posttraumatic stress." (PMID 23185133, 2012). "Moreover, recent research highlights the involvement of ADCYAP1, the gene responsible for encoding the PACAP protein, in several disrupted pathways in neurons derived from schizophrenia patients." (PMID 39596430, 2024). "PAC1 is a G-protein-coupled receptor activated by pituitary adenylate cyclase activating polypeptide (PACAP, Adcyap1), which is a potential schizophrenia susceptibility gene and whose loss of function in mice (PACAP−/−) showed several schizophrenia-related behaviors." (PMID 23964196, 2013).
brain ischemia (6 papers, 2014 to 2023). Diminished or absent blood supply to the brain caused by obstruction (thrombosis or embolism) of an artery resulting in neurologic damage. "We reported previously that Adcyap1+/− mice increased lesion size to compare with the WT mice after brain ischemia and contusion-induced SCI." (PMID 25889720, 2015).
diabetes (5 papers, 2015 to 2025). "Signature genes included previously reported beta-specific genes like NKX6-1, DLK1, and ADCYAP1 (right) and alpha cell–specific genes like IRX2, LOXL4, and DPP4, a cell surface receptor and diabetes drug target." (PMID 27864352, 2017).
cervical cancer (4 papers, 2022 to 2024). A primary or metastatic malignant neoplasm involving the cervix. "ADCYAP1 promoter hypermethylation levels have been linked to cervical cancer development." (PMID 35880088, 2022). "In the case of ADCYAP1R1, its ligand (ADCYAP1) has been previously reported as transcriptionally silenced in cervical cancer." (PMID 38540371, 2024). "Hence, the observed underexpression of ADCYP1R1 in this sample class may indicate an alternative mechanism for the inhibition of ADCYAP1 functions in cervical cancer cells." (PMID 38540371, 2024). "Due to the short coding sequence of ADCYAP1, we could not specifically knock out PACAP in cervical cancer cells." (PMID 37830980, 2023).
breast carcinoma (3 papers, 2009 to 2024). "It was also reported that Adcyap1 can regulate the proliferation and differentiation and was shown to be overexpressed in neuroblastoma and breast cancer." (PMID 19529782, 2009).
insulinoma (3 papers, 2020 to 2024). "Not only did the exogenously added PACAP influence pancreas β cells, but overexpression of Adcyap1 encoding PACAP isoforms led to increased cell survival against cytokine-mediated apoptosis in NIT-1 mouse insulinoma cells." (PMID 35563353, 2022). "Han and Wu found that Adcyap1 overexpression reduced cytokine-induced apoptosis in a mouse insulinoma cell line." (PMID 32765418, 2020).
autism spectrum disorder (2 papers, 2017 to 2022). A spectrum of developmental disorders that includes autism, and Asperger syndrome. "Interestingly, several genes (Adcyap1, Cntnap2, Grid1, Nrxn1, Nrxn3, Ucn, Tbx1, and Nr2e1), that are associated with disorders, stress response, social behaviors or autism spectrum disorders, are up-regulated specifically in the hippocampus of Del/+ mice." (PMID 28704368, 2017). "MR analysis showed that NRSN1 is a protective factor against autism spectrum disorders and eczema, and that ADCYAP1 is protective against oropharyngeal cancer." (PMID 35602164, 2022).
dementia (2 papers, 2020 to 2022). Loss of intellectual abilities interfering with an individual's social and occupational functions. "Valproic acid was identified as a potential therapeutic agent that may regulate the mutual switch genes shared among the dementias (PDE4DIP, NEAT1, LPIN3, ADCYAP1, CCDC136, and ITPKB)." (PMID 32471155, 2020).
dry eye (2 papers, 2013 to 2016). "Taken together, these observations suggest that Adcyap1−/− mice exhibit a dry eye-like phenotype with a reduction in tear volume and corneal damage, despite the structure of the infraorbital lacrimal gland, conjunctiva and neural network of the cornea remaining normal." (PMID 27345595, 2016). "Moreover, Adcyap1−/− mice spontaneously develop corneal keratinization with aging, implying that this mouse phenotype could serve as a novel non-Sjögren's type aqueous-deficient dry eye model arising from lacrimal gland dysfunction." (PMID 27345595, 2016).
endometrial cancer (2 papers, 2020 to 2025). Primary or metastatic malignant neoplasm involving the endometrium (mucous membrane that lines the endometrial cavity). "ADCYAP1 can act as prognostic biomarkers to predict risk of endometrial cancer." (PMID 32218699, 2020).
heart failure (2 papers, 2022 to 2024). Inability of the heart to pump blood at an adequate rate to meet tissue metabolic requirements. "This work also inspires further investigation of the role of Adcyap1, Cartpt, Snca, Sncg, and Th in heart failure and in cardioprotective physiological maneuvers like RIPC." (PMID 39171288, 2024).
atherosclerosis (1 paper, 2023). A disease characterized by the build-up of fatty material and calcium deposition in the arterial wall resulting in partial or complete occlusion of the arterial lumen. "Deficiency of the ADCYAP1 gene encoding pituitary adenylate cyclase-activating peptide (PACAP) aggravates atherosclerosis in ApoE deficient (ApoE−/−) mice." (PMID 37980508, 2023).
Atrophy (1 paper, 2024). Any weakening or degeneration, especially through lack of use. "Of the 808 FTLD-TDP atrophy-correlated HAR genes, 339 correlated negatively and 470 correlated positively with atrophy (ADCYAP1 correlated both positively and negatively with atrophy in at least one FTLD-TDP subtype)." (PMID 38940350, 2024).
brain injury (1 paper, 2022). Acute and chronic (see also brain INJURIES, CHRONIC) injuries to the brain, including the cerebral hemispheres, CEREBELLUM, and brain STEM. "For instance, Ngf, Pdgf-aa, Adap12, ApoE and Adcyap1 have been shown to promote neurogenesis and axonal outgrowth via multifaceted mechanisms following traumatic brain injury 44-47." (PMID 34987639, 2022).
cervical squamous cell carcinoma (1 paper, 2024). A squamous cell carcinoma arising from the cervical epithelium. "The ADCYAP1 gene was found to be overexpressed in cervical squamous cell carcinoma and in adenocarcinoma, which promoted the secretion of PACAP from the cancer cells and led to the dedifferentiation of Schwann cells." (PMID 39766329, 2024).
Cognitive impairment (1 paper, 2023). Abnormal cognition is characterized by deficits in thinking, reasoning, or remembering. "ADCYAP1 knockout mice show cognitive impairment in the novel object recognition test." (PMID 37645701, 2023).
experimental autoimmune encephalomyelitis (1 paper, 2013). An autoimmune demyelinating disease of the central nervous system that is produced experimentally in animals by the injection of homogenized brain or spinal cord in Freund's adjuvant. "We have shown that mice deficient in pituitary adenylate cyclase-activating polypeptide (PACAP, gene name ADCYAP1) manifest enhanced sensitivity to experimental autoimmune encephalomyelitis (EAE), supporting the anti-inflammatory actions described for this neuropeptide." (PMID 23613811, 2013).
gastric cancer (1 paper, 2025). A primary or metastatic malignant neoplasm involving the stomach. "Leveraging the Cancer Genome Atlas (TCGA) dataset, we stratified gastric cancer patients into N0–N3 categories and identified a core set of molecules, including ABCA6, DCLK1, and ADCYAP1, whose expression is tightly linked to LN metastasis." (PMID 41049174, 2025). "We found that molecules such as ABCA6, DCLK1, and ADCYAP1 were linked to higher risk, with DCLK1 and ADCYAP1 being downregulated, while THPO and C5orf46 were upregulated in gastric cancer tissues." (PMID 41049174, 2025). "It was found that molecules like DCLK1 and ADCYAP1 were downregulated, whereas THPO and C5orf46 were upregulated in gastric cancer." (PMID 41049174, 2025).
Insulin resistance (1 paper, 2019). Increased resistance towards insulin, that is, diminished effectiveness of insulin in reducing blood glucose levels. "GDM was associated with insulin resistance and insulin-signaling system may require ADCYAP1 participation." (PMID 31485258, 2019).
ovarian carcinoma (1 paper, 2022). A malignant neoplasm originating from the surface ovarian epithelium. "A significant percentage of ADCYAP1 hypermethylation is frequently reported in ovarian cancer." (PMID 35880088, 2022).
retinal degeneration (1 paper, 2021). Degeneration of the retina. "Adcyap1, which encodes pituitary adenylate cyclase-activating polypeptide (PACAP), was shown to carry neuroprotective properties in retinal degeneration and optic nerve crush models." (PMID 33537951, 2021).
tumor (12 papers, 2005 to 2025). "Among these genes, several immune system genes, such as COL18A1, S100A2, ITGA4, HLA‐C, and ADCYAP1, have previously been linked to tumor progression in PCa." (PMID 39162297, 2024). "Similarly, HAAO and ADCYAP1, which regulate metabolic and angiogenic pathways, are frequently hypomethylated, enhancing tumor growth and immune evasion." (PMID 40528483, 2025). "The low rate of ADCYAP1 hypermethylation in early-stage lesions and its increase with the tumor stage suggest that ADCYAP1 hypermethylation may hinder ADCYAP1's apoptotic action." (PMID 35880088, 2022). "Although various genes such as ADCYAP1, HAND2, MME, and RASSF1A have been reported to exhibit abnormal methylation and tumor development in UCEC, the role of CCND2 gene methylation in UCEC has not been reported." (PMID 40678058, 2025).
cancer (7 papers, 2018 to 2025). A tumor composed of atypical neoplastic, often pleomorphic cells that invade other tissues. "After 2 days, 6 DEG were related to cancer such as Adcyap1, Ramp1, and Trpc3 which were down-regulated." (PMID 29950665, 2018). "ADCYAP1 can act as novel biomarkers for predicting the prognosis of cervical precancer and cancer." (PMID 32218699, 2020). "The most investigated genes were those implicated in neuroendocrine stress responses; dopamine, norepinephrine, and serotonin signalling; apoptosis; insulin secretion; neuroplasticity; reproduction; foetal growth; and cancer (e.g. MAOA, BRSK2, ADCYAP1, BDNF, DRD2, IGF2, H19)." (PMID 41070359, 2025).
Neurological Disease (1 paper, 2015). "The most prominent pathway identified by IPA analysis indicated that this cluster was enriched in "Neurological Disease"-related genes (Adcyap1, Bdnf, CA12, Cdkn1a, Vgf)." (PMID 25803291, 2015).
ADCYAP1 also shares sentences with these, for which no sentence is quoted: Headache (23 papers); Stroke (9); Parkinson disease (8); Cluster headache (6); infection (6); ischemic stroke (5); Alzheimer disease (4); neurodegenerative disease (4); Photophobia (4); acute myocardial infarction (3); cerebral artery occlusion (3); Cerebral ischemia (3); glioblastoma (3); metabolic disorders (3); Nephropathy (3); neuroblastoma (3); peripheral nerve injury (3); rosacea (3); type 2 diabetes (3); cardiac ischemia (2); colon carcinoma (2); glioma (2); headache disorder (2); Huntington disease (2); Hyperglycemia (2); Hypertension (2); injury (2); multiple myeloma (2); Obesity (2); pancreatic cancer (2).
A further 65 diseases each share a sentence with ADCYAP1 in 2 papers or fewer.